INS (insulin)
Diseases named in the same sentence as INS in open-access papers (continued):
Sharing a sentence is not in itself a finding about the gene and the disease.
Insulin resistance (continued). "Additionally, MO influences genes related to adipogenesis, glucose uptake, and insulin resistance; lowers oxidative stress and inflammation linked to obesity; and improves glucose tolerance and insulin signaling, thereby reducing type 2 diabetes risk." (PMID 40149610, 2025). "Future research should improve the diagnostic criteria by incorporating insulin resistance (such as fasting insulin, HOMA-IR), abdominal adiposity measures, other related metabolic factors, and integrating medication history to enhance the precision of metabolic dysfunction assessment." (PMID 40810071, 2025). "However, little is known about the specific molecular mechanisms that cause impaired insulin sensitivity and lead to insulin resistance during perimenopause." (PMID 39823117, 2025). "While insulin use is typically associated with improved glycemic control, it is also linked to weight gain and worsening insulin resistance, which may limit its overall effectiveness." (PMID 40870438, 2025). "Although chronic elevations are associated with insulin resistance, acute elevations may enhance insulin sensitivity." (PMID 41141350, 2025). "It is well known that T2DM is caused by insufficient insulin secretion or insulin resistance." (PMID 39812542, 2025). "DM is characterized by significantly elevated glucose levels caused by issues with insulin production or insulin resistance; some individuals may experience both factors." (PMID 40059876, 2025). "A central mechanism underlying these associations is insulin resistance (IR), a condition in which peripheral tissues such as muscle, liver, and adipose tissue exhibit a diminished response to insulin, prompting compensatory pancreatic hypersecretion in order to maintain normal blood glucose levels." (PMID 40648978, 2025). "Furthermore, metabolic disturbances associated with obesity, such as glucose tolerance, insulin resistance, fasting serum insulin levels, and serum lipid levels, were all markedly improved in TRIM56‐overexpressing mice." (PMID 39928840, 2025). "For instance, variants that reduce GLUT4 expression or impair its insulin responsiveness may increase the risk of insulin resistance and, ultimately, T2D." (PMID 40854653, 2025). "Insufficient physical activity can also negatively affect insulin sensitivity and may contribute to the emergence of insulin resistance, which is a key risk factor for type 2 diabetes." (PMID 40218939, 2025). "It has been suggested that insulin resistance could be a causative factor in the onset of metabolic syndrome, which is marked by reduced tissue sensitivity or response to circulating insulin." (PMID 39997933, 2025). "GIP is associated with insulin resistance, as its levels increase, as shown by our results, and therefore the increase in insulin secretion may also be, at least in part, secondary to increases in insulin resistance." (PMID 40214973, 2025). "Brain insulin resistance, defined as deficient insulin effect transmission due to reduced insulin receptor (IR) density or impaired cellular signaling pathway, has also been described in the context of AD progression, existing independently of peripheral insulin sensitivity." (PMID 40430434, 2025). "This is particularly important not only due to the critical role of insulin in fetal development, but also because maternal insulin resistance is linked to metabolic dysregulation in the mother, which may have multiple downstream effects." (PMID 41007299, 2025). "Notably, prior studies that did not restrict PV at enrolment observed similar associations between higher fasting insulin or insulin resistance and larger prostate size." (PMID 40955380, 2025). "Chronic activation of pro-inflammatory pathways in insulin action target cells may be a factor in obesity, insulin resistance, and associated metabolic diseases, such as type 2 diabetes." (PMID 41044118, 2025).
Insulin resistance (continued). "Interestingly, boosting cellular GSH to detoxify 4-HHE prevents its associated insulin resistance, further underscoring the impact of lipid peroxidation on skeletal muscle insulin sensitivity." (PMID 41226411, 2025). "Therefore, decreased insulin sensitivity (insulin resistance) significantly increases the risk of MetS." (PMID 41171818, 2025). "Reduced physical activity and obesity cause a decrease in insulin sensitivity, which when combined with a genetic predisposition to insulin resistance prompts pancreatic β-cells to increase insulin production in an attempt to compensate for the ineffective insulin response." (PMID 40647906, 2025). "On the contrary, CR diets in GDM may also result in weight loss promoting improved insulin sensitivity and decreased insulin resistance thereby reducing the GDM-associated adverse outcomes." (PMID 40078500, 2025). "Pathway analysis revealed that proteins linked to fatty acid degradation, oxidative phosphorylation, and mitochondrial protein content positively correlated with insulin sensitivity, while Wnt signalling, and ubiquitin and lysosome proteolysis were directly associated with insulin resistance." (PMID 41028721, 2025). "Several animal studies reported that long-term caffeine intake is inversely associated with insulin resistance through various mechanisms, including improved insulin/IGF-1 signaling via the induction of insulin receptor substrate 2 or a decrease in circulating catecholamines." (PMID 40362793, 2025). "Finally, vWAT-regulated insulin resistance is a critical condition, as peripheral insulin resistance is a well-established risk factor for AD, leading to impaired brain glucose metabolism and insulin signaling, which are hallmarks of the disease." (PMID 41157172, 2025). "Notably, insulin resistance, a hallmark of metabolic syndrome, elevates circulating insulin and alters lipid metabolism." (PMID 40227756, 2025). "Moreover, insulin resistance can cause pancreatic beta cells to secrete excessive insulin, negatively impacting the vasculature." (PMID 41227046, 2025). "Specifically, cardiorespiratory fitness can modulate leptin’s signaling pathway in skeletal muscles, while higher levels of leptin are associated with higher levels of insulin and, consequently, with insulin resistance, due to a break in the insulin signaling pathway caused by hyperinsulinemia." (PMID 39860463, 2025). "Furthermore, 2 h insulin levels showed a significant positive correlation with testosterone levels (r = 0.32, p =< 0.01), suggesting that greater insulin resistance is linked to higher androgen production." (PMID 40868057, 2025). "Abnormal mitochondrial function may cause insulin resistance and insufficient insulin secretion, which leads to an increase in blood sugar, thus causing diabetes." (PMID 40438494, 2025). "This may be explained by the increased insulin resistance associated with higher body weight, where elevated insulin levels during OGTT might reduce glucose levels and thus lower the sensitivity of the test." (PMID 40951687, 2025). "Additionally, TMEM127 has been implicated in metabolic disorders such as insulin resistance and fatty liver disease, with studies demonstrating a strong correlation between its expression levels and insulin sensitivity." (PMID 41357074, 2025). "Evidence indicates that deficiencies in calcium and magnesium may increase the risk of GDM by impairing insulin secretion and promoting insulin resistance." (PMID 41235310, 2025). "Dysfunctional variants may impair insulin release, contributing to insulin resistance, which in turn affects HDL synthesis and reverse cholesterol transport." (PMID 40981175, 2025). "Various studies stated that high and fluctuating glucose levels are a major risk factor in the development of insulin resistance and altered insulin secretion, which may result in T2DM via progressive β-cell dysfunction." (PMID 40806123, 2025).
Insulin resistance (continued). "The results of this study indicate that Type 2 diabetes or insulin resistance associated with obesity is linked to altered insulin signaling pathways, as evidenced by a significant increase in the activities of DPP-4 and PTP1B in the serum by 97% and 118%, respectively, compared to normal rats." (PMID 40376699, 2025). "Excess visceral fat also causes insulin resistance and increases insulin levels." (PMID 40140188, 2025). "The insulin signaling pathway may be inhibited by an increase in reactive oxygen species (ROS), which cause insulin resistance and have been associated with various brain disorders, including depression." (PMID 40175334, 2025). "Nevertheless, it remains controversial whether obesity alters glucose uptake since insulin resistance is strongly associated with reduced glucose uptake in insulin-responsive tissues." (PMID 40825507, 2025). "In addition, insulin resistance caused by obesity leads to higher insulin requirements and complicates achieving optimal glycemic control and weight management in T1DM." (PMID 41585812, 2025). "These hormonal shifts indicate an initial insulin resistance and impaired insulin response in preterm infants, which may predispose them to metabolic dysfunction as they grow." (PMID 40519768, 2025). "For instance, C. albicans overgrowth, a prevalent species within the Candida genus, has been mechanistically linked to insulin resistance in MetS by disrupting gut mucosal barriers, increasing permeability, and promoting endotoxemia that impairs insulin signaling in peripheral tissues." (PMID 40969753, 2025). "These metabolic improvements were accompanied by the downregulation of hepatic monoacylglycerol acyltransferase 1 (MGAT1), a gene implicated in insulin resistance and hepatic glucose metabolism, further supporting its role in improving glucose homeostasis under insulin-resistant conditions." (PMID 40565007, 2025). "Protein intake is associated with improved insulin sensitivity as well as maintenance of muscle mass, and micronutrients such as vitamins B and D, and calcium have also been reported to have a positive influence on insulin resistance." (PMID 41010533, 2025). "Elevated resistin levels are associated with insulin resistance; targeting resistin could help manage inflammation and improve insulin function." (PMID 40013194, 2025). "A high adipocyte lipolysis rate and excessive NEFA release have been associated with insulin resistance; therefore, inhibiting lipolysis may improve insulin sensitivity." (PMID 40210728, 2025). "Hence, in Black individuals, it seems that insulin and insulin resistance, as well as blood glucose, can cause end-organ changes." (PMID 40283533, 2025). "In addition, the score was associated with insulin resistance inversely, and insulin sensitivity positively (beta: -0.217; 95% CI: -0.273, -0.161 for HOMA-IR, and 0.258 (0.206, 0.310) for QUCKI)." (PMID 41286497, 2025). "In one study, it was shown that female mice lacking ERα globally did not exhibit insulin resistance in skeletal muscle but showed decreased insulin suppression of hepatic glucose production during a euglycemic, hyperinsulinemic clamp, suggesting hepatic insulin resistance due to ERα deficiency." (PMID 40278371, 2025). "Notably, increased accumulation of lipid metabolites in skeletal muscle is observed both in endurance exercise—associated with improved insulin sensitivity—and in high-fat diets that induce insulin resistance." (PMID 40862756, 2025). "The observation that the metabolic condition (fasting vs insulin stimulation) was an important determinant of the association between insulin resistance and BGM was previously made by others, but few studies tested the hypothesis." (PMID 39185744, 2025).
Insulin resistance (continued). "Women with PCOS tend to have hypertrophic adipocytes—larger fat cells—rather than hyperplastic expansion (an increased number), and hypertrophic adipose tissue is closely associated with insulin resistance due to reduced insulin sensitivity at the cellular level." (PMID 40729034, 2025). "However, increased NKT cell activity can also increase inflammatory processes and thereby increase insulin resistance, causing the pancreas to produce larger amounts of insulin." (PMID 40559402, 2025). "However, as insulin resistance persists, pancreatic β-cell dysfunction and loss occur, ultimately leading to inadequate insulin production and worsening hyperglycemia." (PMID 40286055, 2025). "Dietary patterns characterized by the excessive consumption of simple sugars, high-glycemic index (GI) foods, and processed carbohydrates have been associated with elevated postprandial glucose and insulin levels, promoting hyperinsulinemia and insulin resistance." (PMID 40733002, 2025). "Low insulin levels have been shown to be associated with sarcopenia and functional measures of sarcopenia, such as body weight, muscle mass, and muscle strength, suggesting that insulin resistance is involved in the pathogenesis of sarcopenia." (PMID 40559405, 2025). "Additionally, elevated levels of leptin have been associated with insulin resistance, while adiponectin is known for its insulin-sensitizing effects." (PMID 40806358, 2025). "Additionally, sugar-sweetened beverages (SSBs) are associated with increased insulin resistance, higher insulin levels, and elevated leptin levels, particularly in men and non-overweight women." (PMID 40873447, 2025). "VD plays a role in glucose metabolism and insulin sensitivity, suggesting that its deficiency may exacerbate insulin resistance and, consequently, fertility-related complications." (PMID 40076878, 2025). "As the NAFLD is closely linked to insulin resistance, while lipid buildup in insulin-sensitive tissues leads to lipotoxicity and insulin resistance, lipid synthesis via DNL remains high during insulin resistance, potentially creating a cycle of lipid-induced insulin resistance." (PMID 40034298, 2025). "Vitamin D deficiency during pregnancy may affect insulin secretion and increase insulin resistance, leading to an increased risk of GDM." (PMID 39963668, 2025). "In addition, normally, Phosphoinositide 3‐kinase (PI3K) regulates insulin signaling, and its inactivating mutations are associated with insulin resistance (IR)." (PMID 40625625, 2025). "Increased phosphocholine deteriorates insulin signalling and causes insulin resistance." (PMID 40732347, 2025). "Moreover, oxidative stress disrupts the action of insulin by modulating cell signaling pathways, causing the sensitivity of tissue cells to insulin to decline and thus giving rise to insulin resistance." (PMID 39974734, 2025). "Biologically, premenopausal females are conferred protection by estrogen, which enhances insulin sensitivity and promotes a more favorable subcutaneous fat distribution, while males are more prone to visceral adiposity, a major risk factor for insulin resistance." (PMID 41199866, 2025). "Insulin resistance was positively associated with HbA1c and daily insulin dose during treatment." (PMID 39998445, 2025). "HEI, characterized by higher consumption of nutrient-dense foods, may enhance insulin sensitivity and reduce insulin resistance, thereby mitigating MASLD risk." (PMID 40245006, 2025). "Women with PCOS may be more susceptible to health issues such as insulin resistance due to the direct effect of TGFβ on glucose uptake and insulin signalling, as well as its potential to hinder glucose transport into muscle." (PMID 41595448, 2025). "Additionally, VAT is associated with insulin resistance and elevated insulin and insulin-like growth factor (IGF) levels, which activate cell proliferation pathways, such as PI3K/AKT and MAPK, thus creating a systemic environment that favors tumor growth." (PMID 40500581, 2025).
Insulin resistance (continued). "Insulin resistance, a hallmark of type 2 DM, is characterized by an impaired biological response to insulin in its target tissues, primarily the liver, muscle, and adipose tissue, leading to hyperinsulinemia as a compensatory mechanism and eventual pancreatic β-cell exhaustion." (PMID 40429763, 2025). "Dr. Corkey proposed that environmental risk factors, combined with a genetic predisposition, could lead to elevated basal insulin levels, which, in turn, might be the root cause of insulin resistance, obesity, and type 2 diabetes." (PMID 40364246, 2025). "Similarly, by blocking insulin signaling, extracellular miR-27a elevation in response to obesity causes insulin resistance." (PMID 40565979, 2025). "Since T2D in Asia involves both insulin resistance and deficient insulin secretion, both of which are differently affected by alcohol, we prospectively examined whether the association differs according to body mass index (BMI) categories among the Japanese." (PMID 39924248, 2025). "Moreover, dysregulated insulin/insulin-like growth factor signaling and insulin resistance in the central nervous system have been associated with an elevated risk of dementia, including Alzheimer's disease." (PMID 40825507, 2025). "Insulin resistance appears to further drive this adverse thrombotic phenotype, suggesting an enhanced platelet-driven cardiovascular risk in those with type 1 diabetes and reduced insulin sensitivity." (PMID 40304758, 2025). "In contrast, T2D, which accounts for 90–95% of those with diabetes, involves a complex interplay between genetics and environmental factors and ranges from predominantly insulin resistance with relative insulin deficiency to predominantly impaired insulin secretion with insulin resistance." (PMID 39997999, 2025). "Moreover, iron overload has been closely linked to insulin resistance, potentially by impairing insulin signaling and reducing insulin sensitivity, thereby facilitating hepatic fat accumulation." (PMID 41001677, 2025). "Excess anti-incretin signals, perhaps stimulated by macronutrient composition or chemical additives in modern diets, might cause insulin resistance, reduced insulin secretion, and β-cell depletion, leading to T2DΜ." (PMID 40864811, 2025). "In dairy cows, maternal insulin resistance during late gestation is associated with altered metabolic traits in the subsequent pre-weaned calf with increased plasma insulin concentrations and similar serum glucose concentrations in offspring from insulin resistant cows." (PMID 40746487, 2025). "Insulin resistance and decreased insulin production are the primary pathogenic mechanisms underlying type 2 diabetes, significantly disrupting glucose metabolism and triggering a cascade of oxidative stress and inflammatory reactions that exacerbate the condition." (PMID 40958722, 2025). "Insulin resistance (IR) is strongly associated with a chronic low-grade inflammatory state, this chronic inflammation interferes with insulin signalling and reduces insulin bioavailability through direct or indirect mechanisms." (PMID 41488463, 2025). "Postoperative insulin resistance has been linked to nausea and vomiting, catabolism, impairment of well-being and but it can be limited or prevented by insulin, preoperative infusion or oral administration of a carbohydrate-rich drink, primarily composed of maltodextrins." (PMID 40823584, 2025). "Moreover, insulin resistance and excess weight gain due to intensive insulin therapy can increase cardiovascular risk factors (e.g., hypertension, dyslipidemia)." (PMID 40004833, 2025). "This hypothesis is supported by studies demonstrating elevated CRC risk in insulin‐treated patients with higher baseline insulin resistance." (PMID 39980820, 2025). "The persistent association of mtDNA DAMPs with insulin resistance post-intervention suggests that mitochondrial stress may contribute to impaired insulin signaling independently of traditional inflammatory markers." (PMID 41156500, 2025).